IL10 (interleukin 10)
Diseases named in the same sentence as IL10 in open-access papers (continued):
Sharing a sentence is not in itself a finding about the gene and the disease.
mastitis (38 papers, 2009 to 2025). Inflammation of breast tissue during lactation or postpartum due to an obstructed duct or infection. "Greater concentrations of Th2-associated cytokines, such as IL-4 and IL-10, were detected in milk from CM affected women the week before mastitis detection." (PMID 39896819, 2024). "This study looks at expressions of genes, such as IL-4, IL-10, and IFNγ, linked to immune response mechanisms in mastitis." (PMID 35445115, 2022). "There is increase in the level of Th1 and Th2 type cells in mammary gland mediated by proinflammatory cytokines when infected by S. aureus causing mastitis; the release of proinflammatory cytokines is tightly regulated by the production of IL-10 cytokine." (PMID 27733800, 2016). "In order to characterize the expression of genes associated with immune response mechanisms to mastitis, we quantified the relative expression of the IL-2, IL-4, IL-6, IL-8, IL-10, IFN-γ and TNF- α genes in milk cells of healthy cows and cows with clinical mastitis." (PMID 21637453, 2009). "In addition, analysis of the structure of the genes that were differentially expressed in this study, such as IL-10, would be useful to identify marker SNPs for mastitis resistance and susceptibility." (PMID 21637453, 2009). "The SCC and levels of generated cytokines (interleukin (IL)-1, IL-2, IL-4, IL-5, IL-6, IL-8, IL-10, and IL-12) in milk increase in both naturally occurring and experimentally induced mastitis." (PMID 40303387, 2025). "During mastitis, IL-10 functions as an anti-inflammatory factor, although its concentration can vary depending on the etiological determinants and the stage of infection." (PMID 41226434, 2025). "For milk, bovine IL-10 FF concentrations in our cohort, which were in hundreds of pg/mL, exceeded milk IL-10 means reported by ELISA in bovine subclinical and clinical mastitis." (PMID 41226434, 2025). "(2020) compared the healthy cows with cows with subclinical and clinical mastitis and found that the IL‐10 level was significant in cows with subclinical mastitis, and it was significantly higher in cows with clinical mastitis." (PMID 39792067, 2025). "Mouse mastitis from S. simulans and S. aureus superinfection was associated with a decrease in GM-CSF but an increase of TNF-α and the anti-inflammatory IL-10." (PMID 40757863, 2025). "In this study, when the serum cytokine levels of the animals with mastitis were analysed according to the type of parturition, the IL‐10 level was found to be higher in the D group." (PMID 39792067, 2025). "(2017) found that the serum level of anti‐inflammatory IL‐10 in cows with subclinical mastitis was significantly lower than in healthy cows." (PMID 39792067, 2025). "(2020) investigated IL‐10 levels in cows with clinical mastitis or subclinical mastitis and healthy dairy cows and found that this cytokine was significantly lower in animals with clinical mastitis compared to the other two groups." (PMID 39792067, 2025). "In 2017, average concentrations of IL-4, IL-6, and IL-10 in subclinical mastitis milk with CNS were reported as lower than the values from this study." (PMID 39195804, 2024). "In the current study, the changes in IL-4, IL-6, and IL-10 were consistent with previous experiments, which proves that lentinan is beneficial for reducing subacute mastitis." (PMID 38731317, 2024). "This study aimed to determine the relationships of IL-4, IL-6, and IL-10 in mastitis milk with concurrent infection, bacterial pathogens, SCC, and MDA, an oxidative stress marker." (PMID 39195804, 2024). "In our study, IL-10 expression was significantly elevated in mammary cells of mastitis-affected mice, suggesting that IL-10 actively exerts an anti-inflammatory effect at this time to control the extent of the inflammatory response to reduce tissue damage." (PMID 37189805, 2023).
mastitis (continued). "Inflammatory cytokine interleukin (IL-10), IL-4, and interferon-gamma (IFNγ) expression genes were measured and compared in mastitis-free and mastitis-affected animals." (PMID 35445115, 2022). "The expressions of IL-10, IL-4, and IFNγ genes were contrasted in mastitis-free and mastitis-affected animals." (PMID 35445115, 2022). "In mastitis, IL-10 production highly increases, reaching superior relative numbers over other factors." (PMID 35335696, 2022). "IL-10, and IFNγ genes were differentially expressed in mastitis and healthy conditions (p ˂ 0.01), indicating that these genes are strong indicators of mastitis in the conditions studied." (PMID 35445115, 2022). "Mastitis caused by Gram-positive and Gram-negative bacteria was used to assess the expressions of IL-4, IL-10, and IFNγ genetic features connected to the immune system response pathways to mastitis." (PMID 35445115, 2022). "These genes are strong predictors of mastitis in the states analyzed, as evidenced by the differential expression in mastitis and healthy conditions of the IL-4, IL-10, and IFNγ genes." (PMID 35445115, 2022). "The transforming growth factor beta induced (TGFBI) and IL-10 cytokines are upregulated during E. coli mastitis, as anti-inflammatory cytokines, and persist for the period of the inflammatory response." (PMID 34637035, 2021). "In the present study, HSCC cows had lower levels of pre-partum serum IL-10 than LSCC cows, leading to decreased inflammation resistance, and an increased postpartum mastitis risk." (PMID 32408873, 2020). "We analyzed TNF-α, IL-1β, IL-6 and IL-10 levels in mouse mastitis model and the mammary epithelial cells by qRT-PCR and ELISA." (PMID 29340029, 2017). "These cell subsets can release chemokines and inflammatory cytokines, such as CXCL10, CCL2, CCL20, IL-17, IL-12, IFN-γ, IL-1β, IL-6, TGF-β and IL-10, which are significantly increased in the milk of dairy ruminants with mastitis." (PMID 26230498, 2015). "In summary, Th1, Th2 and Th17 cells are all activated for efficient immunity against S. aureus infection in a murine mastitis model but are tightly regulated by Treg cells and IL-10." (PMID 26230498, 2015). "IL-10 gene expression was higher in the group of BW and Gyr cows with mastitis compared to animals free of infection from both breeds (p < 0.05)." (PMID 21637453, 2009). "In a large bovine clinical mastitis study, milk cytokines, including IL-10, were quantified in whey prepared by high-speed defatting and reported in activity units (U/mL), which prevents direct conversion to mass concentration and complicates cross-study comparisons." (PMID 41226434, 2025). "Similarly, the analysis of immune modulation by L. rhamnosus strains on mastitis identified two strains with significant anti-inflammatory potential, which can strongly induce IL-10 and weakly secrete pro-Th1 cytokine (IL-12 and IFN-γ)." (PMID 39399489, 2024). "Additionally, noted reduced concentrations of IL-10 in the milk and serum of cows who had subclinical mastitis." (PMID 38481237, 2024). "Therefore, this study aimed to determine the relationships of IL-4, IL-6, and IL-10 in mastitis milk with concurrent infections, bacterial pathogens, SCC, and oxidative stress." (PMID 39195804, 2024). "This study examines the correlation between interleukin-4 (IL-4), interleukin-6 (IL-6), and interleukin-10 (IL-10) levels in mastitis milk and concurrent infections, bacterial pathogens, somatic cell counts (SCCs), and malondialdehyde (MDA), an oxidative stress marker." (PMID 39195804, 2024). "In addition, the expression levels of IL-10 in the mammary tissue of mice in the lipopeptide-treated and antibiotic-treated groups were extremely significantly lower than those in the mastitis-untreated group." (PMID 37189805, 2023). "Cows with mastitis had higher levels of IL-10 gene expression than healthy animals in the sample." (PMID 35445115, 2022).
mastitis (continued). "Similarly, separate analysis of BW Holstein cows also showed a higher expression of the IL-10 gene in animals with mastitis compared to animals free of infection." (PMID 21637453, 2009). "DEGS such as IL10, CCL5, IL1B, OSM, TNFRSF1B, IL7, and CCR3, among others, implicated in these pathways, may play a crucial role in the development of subclinical mastitis in Bactrian camels, though further analysis is needed to explore their potential functions." (PMID 40005880, 2025). "However, the immunological profile of milk samples revealed remarkable differences, mainly related to the components of the adaptive immune system, depending on the etiological agent of mastitis, with IL10 and IL13 being detected in the samples from SAM cases but not in those of AM cases." (PMID 35079053, 2022). "The differentially expressed genes in bovine lymphocytes regulated by H3K27me3 on upstream 2 kb regions (IL10, PTX3 and etc.)may relate to S. aureus mastitis susceptibility and could be considered as key candidate genes for anti- S. aureus mastitis study and breeding." (PMID 27503467, 2016). "Consequently, H3K27me3 levels in healthy cows were higher than in S. aureus mastitis cows for both genes (CD4 and IL10), which means that increased H3K27me3 level repressed pro-inflammatory gene expression (IL10) in healthy dairy cattle and vice versa in S. aureus mastitis cows." (PMID 27503467, 2016). "We assumed that third-parity cows may be infected by subclinical mastitis by the following mechanisms: due to low level of H3K27me3 modification of IL10, more IL10 released by cytotoxic T-cells could inhibit the actions of NK cells during the immune response to bacterial infection." (PMID 22761725, 2012). "Both experimentally induced or naturally occurring mastitis results in an increase in the somatic cell count (SCC) and levels of produced cytokines (interleukin (IL) IL-1, IL-2, IL-4, IL-5, IL-6, IL-8, IL-10, and IL-12) in milk." (PMID 35335696, 2022). "Through bioinformatics investigation, IL8, IL10, IL18, and CTSC were recognized as the essential biomarkers for E. coli mastitis and were related to the immune response of bovine mastitis." (PMID 34637035, 2021). "We analyzed the anti-inflammatory effects of Se on S. aureus mastitis by determining protein and mRNA levels of TNF-α, IL-1β, IL-6 and IL-10 by ELISA and qRT-PCR, respectively." (PMID 29340029, 2017). "TLR2, NOD2, and inflammatory cytokines (TNF-α, IL-1β, IL-6, CXCL1, IL-10, TGF-β1, and IFN-γ) are involved in the response to mastitis induced by S. aureus." (PMID 25990971, 2015). "Comparison of the relative gene expressions of IL-10, IL-4, and IFNγ in animals with and without mastitis and the respective significance level of the means." (PMID 35445115, 2022). "The expression of the IL-10 gene was significantly higher (p < 0.001) in mastitis-affected cows than noninfected animals." (PMID 35445115, 2022). "Compared with animals without mastitis, IL-10 gene expression was higher in cows with mastitis (p < 0.001)." (PMID 35445115, 2022). "For one site on promoter region of IL10 gene (TSS: 3572215), the relative enrichment levels were consistent with the results in ChIP-seq that the enrichments for healthy cattle were higher than for mastitis cattle (Fig. 8a8 & b3)." (PMID 27503467, 2016). "Statistical analysis of transcript and protein level expression changes indicated that 10 genes, namely TLR4, MyD88, IL-6, and IL-10, were up-regulated, while, CD14, TNF-α, MD-2, IL-β, NF-κB, and IL-12 were significantly down-regulated in mastitis tissue in comparison with normal tissue." (PMID 25706977, 2015). "Therefore, up-regulation of IL-10 expression in bPBLs, suggesting that IL-10 may be regulated by PTK2B and SYK, and thus participate in the regulation of inflammatory response in dairy cow mastitis." (PMID 31447828, 2019).
mastitis (continued). "No significant change in gene expression of IL-2, IL-4, IL-6, IL-8, IL-10, IFN-γ, and TNF-α by real-time PCR in milk among animals without mastitis vs. animals with mastitis was observed." (PMID 35335696, 2022). "For this purpose, the expression of the interleukin 2 (IL-2), IL-4, IL-6, IL-8, IL-10, interferon gamma (IFN-γ) and tumor necrosis factor alpha (TNF-α) genes was investigated in Black and White (BW) Holstein and Gyr cows with and without clinical signs of mastitis." (PMID 21637453, 2009).
ulcer (38 papers, 2011 to 2026). "In the present ulcer trial, ethanol ingestion caused up‐regulation of pro‐inflammatory mediators and reduced IL‐10 cytokine release, as seen in ulcer controls." (PMID 40034223, 2025). "In light of the epithelial barrier defect in ulcerating disease that predisposes to bacterial translocation, we tested whether exposure of monocytes to bacteria can induce functional IL-10 resistance." (PMID 33037057, 2021). "In an in-vivo oral mucositis model, the microneedle system accelerated mucosal healing, normalized inflammatory and angiogenic markers (VEGF, TNF-α, NF-κB, and IL-10), and achieved nearly complete ulcer recovery when compared to standard treatments." (PMID 40676449, 2026). "The reference rats showed a better serum inflammatory profile (lower TNF‐α, and IL‐6 levels and increased IL‐10 cytokines) than the ulcer controls." (PMID 40034223, 2025). "Their study identified interleukin-10 (IL-10) and uric acid as key markers for differentiating ulcer severity." (PMID 40756392, 2025). "Rats treated with Schiff base compound meaningfully condensed TNF-α and IL-6, increased IL-10 quantities, and related ulcer control group." (PMID 39830532, 2024). "TNF-α, IL-6, and IL-10 are significantly higher in ulcer control group compared to the fed with omeprazole or Schiff base compound." (PMID 39830532, 2024). "Reductions in serum and gastric IL-10 levels due to ulcer inductions were abolished by both NPW and omeprazole, but elevation in IL-10 was statistically significant only in the gastric tissue of omeprazole-treated ulcer group (p < 0.001)." (PMID 38227096, 2024). "Prévot and colleagues analysed the lesions of 14 patients in French Guiana, demonstrating high IL-10 but low IFN-γ mRNA levels in ulcers compared to high intralesional IFN-γ but low IL-10 mRNA levels in nodular lesions." (PMID 37384606, 2023). "To evaluate the anti-inflammation of the AAEs in ulcers, we detected the levels of proinflammatory and anti-inflammatory cytokines, including IL-1β, IL-6, and IL-10 in the serum." (PMID 34580595, 2021). "The mechanisms of gastric injury have not been fully clarified, but it is well known that proinflammatory mediators played an important role in the development of ulcer, including IL-6, IL-10, tumor necrosis factor-α (TNF-α), and NF-κB." (PMID 34580595, 2021). "Manuka honey elevated the IL-10 levels in the honey-treated group in comparison to the ulcer control group." (PMID 28250794, 2017). "The data obtained in this study revealed that IL-10 levels were significantly decreased in the ulcer control group." (PMID 28250794, 2017). "This signified that although eAE treatment reduced inflammatory cytokine levels, the inhibitor study showed that tissue IL-10 level played a key immunomodulatory role for the augmentation of eAE-induced ulcer healing." (PMID 21076542, 2011). "Rats given ethanol had a 33.12% decrease in IL-10 level when compared with the control group, whereas those with ulcers and exposed to either protection or treatments with FDWF or famotidine had an increase of 12.33, 23.40, and 31.53%, respectively, when compared with the ulcerogenic group." (PMID 36840885, 2023). "Some studies on BD have observed a reduction in IL-10 protein level in BD patients’ peripheral blood and aqueous humor, while in other studies, there has been an increase in the concentration of this protein in plasma and active ulcers of BD." (PMID 31889911, 2019). "The ulcer control rats showed the highest inflammation rate represented by higher TNF‐α, IL‐6 cytokines, and lower IL‐10 levels compared to all groups." (PMID 40034223, 2025). "In comparison with the control group, IND-treated rats showed visible multiple ulcers with ulcer index, serum MDA, IL-2 and IL-6 were elevated while IL-10, PGE2, NO, and eNOS mRNA expression were significantly reduced." (PMID 33833690, 2021).
ulcer (continued). "We analyzed the ulcer area, conducted histological analysis, and measured the levels of the inflammatory cytokines TNF-α, IL-6, IL-1β, and IFN-γ, and anti-inflammatory cytokine IL-10 by ELISA." (PMID 35456589, 2022). "Various cytokines may contribute to the pathogenesis of ulcers, as elevated IL-2, IFN-γ, and TNF-α, while lower concentrations of IL-10 were reported in lesions of RAS patients." (PMID 23258985, 2012). "In the gastric tissue and serum samples of saline-treated ulcer group, levels of the pro-inflammatory cytokines TNF-α and IL-1β were both elevated as compared to control group (p < 0.001), while the anti-inflammatory IL-10 level was depressed (p < 0.001–0.001)." (PMID 38227096, 2024). "Low IL-10 has also been observed in wound margins of non-healing ulcers." (PMID 35836916, 2022). "Furthermore, comparing patients with leg ulcers with patients without ulcers, sICAM-1 (ng/mL) (141.8 (257.41) vs. 0.41 (107.3); p = 0.0152), but not IL-10 (ng/mL) (11.01 (15.95) vs. (2.98 (11.92) was significantly greater in the ulcer group." (PMID 23922670, 2013). "Decreased production of IL-10 due to an ATA haplotype of −1082/+819/+592 polymorphism in the IL-10 gene can lead to a stronger inflammation in H. pylori-infected patients and might be associated with a risk of ulcer disease or non-cardia GC development." (PMID 34440074, 2021). "IL10 mRNA levels in freshly isolated PBMCs from infected patients were 3.8-fold higher than the uninfected group (p = 0.001), and there was a 4.8-fold higher mRNA level in the samples from infected patients without peptic ulcer disease compared to those who had ulcers (p = 0.017)." (PMID 27014260, 2016). "In such cases, the absence of a positive correlation between IL-10 not only with TNF and IFN-γ, but also with other pro-inflammatory cytokines at the lesion site suggests an impaired participation of IL-10 in the control of the inflammatory reaction resulting in tissue injury and ulcer development." (PMID 38535542, 2024).